NDRG1 (N-myc downstream regulated 1)
Diseases named in the same sentence as NDRG1 in open-access papers (continued):
Sharing a sentence is not in itself a finding about the gene and the disease.
infection (10 papers, 2012 to 2023). The state of being infected such as from the introduction of a foreign agent such as serum, vaccine, antigenic substance or organism. "However, it remains to be understood what other pathological events can be triggered by studying the NDRG1-DGAT-Lipid droplets complex associated with infections by this virus." (PMID 37513023, 2023). "In this sense, the studies in which a deregulation of lipid droplets has been observed that infection by this virus causes an up-regulation of NDRG1 and DGAT proteins and these in turn promote an exacerbation of lipid droplets could be associated with lipotoxicity events in the animal." (PMID 37513023, 2023). "For the loss-of-function study, qRT-PCR analysis revealed the successful downregulation of Ndrg1 after the infection of the Ndrg1 shRNA lentivirus in primary BMSCs." (PMID 35120575, 2022). "For the gain-of-function study, qRT-PCR analysis revealed the successful overexpression of Ndrg1 in primary BMSCs following the infection of the Ndrg1 expression lentivirus." (PMID 35120575, 2022). "Like the phosphorylation of SGK1, infection of P. gingivalis indeed elevated phosphorylation of NDRG1 at threonine 346/356/366 in all cells we investigated." (PMID 35588785, 2022). "Among the proteins that were most robustly upregulated in cells infected with YopJC172A-expressing Y. pseudotuberculosis in comparison to wild-type infection, NDRG1 (Q92597) was one of the top hits (FC = 35), followed by JUN (P05412, FC = 23)." (PMID 34319170, 2021). "Cells expressing sh-control or sh-NDRG1 were incubated on ice with a high multiplicity of infection (MOI) of PRRSV for 1 h, and viral binding was assayed by RT-qPCR." (PMID 31189711, 2019). "Remarkably, the prevailing view is that KS is derived from endothelial cells and that PEL is derived from B cells that are permissive to KSHV infection, suggesting that KSHV might specifically upregulate NDRG1 in these cells to facilitate infection." (PMID 30811506, 2019). "However, whether NDRG1 associates with KSHV during infection and plays a role in KSHV persistence has not yet been determined." (PMID 30811506, 2019). "We found that DDIT4, CTH, RELB, and SLC7A11, but not NDRG1 and CHAC1, increased in gastric tissues at 4 months post-infection (MPI)." (PMID 32457731, 2020).
peripheral neuropathy (4 papers, 2008 to 2025). A disorder affecting the peripheral nervous system. "There are only two early-onset peripheral neuropathies with a known genetic basis in dogs; both being autosomal recessive conditions due to mutations in the NDRG1 gene." (PMID 25275565, 2014). "Recently, a clinical GWAS with 1040 patients treated with paclitaxel identified 3 SNPs located in the EPHA5, FGD4 and NDRG1 genes that were associated with peripheral neuropathy." (PMID 23006423, 2012). "A previous GWAS from an ongoing phase III clinical trial, CALGB 40101, identified 3 top SNPs located in the EPHA5, FGD4 and NDRG1 genes that were associated with paclitaxel-induced peripheral neuropathy, although none reached genome-wide significance." (PMID 23006423, 2012).
genetic diseases (2 papers, 2024 to 2025). "Charcot–Marie–Tooth neuropathy type 4D (CMT4D) is a rare genetic disorder of the peripheral nervous system caused by biallelic mutations in the N-Myc Downstream Regulated 1 gene (NDRG1)." (PMID 39201732, 2024).
metabolic disease (2 papers, 2022 to 2025). A congenital disorder (due to inherited enzyme abnormality) or acquired (due to failure of a metabolically important organ) disorder resulting from an abnormal metabolic process. "Gene annotation based on the TWAS database highlighted significant associations between several of these candidate genes (such as SPP1, FAM13A, NDRG1, and IER3) and key bovine health traits, including milk protein percentage, body depth, and ketosis (a metabolic disease of dairy cow) susceptibility." (PMID 40521032, 2025).
disease of the peripheral nervous system (1 paper, 2023). "Although CMT is described as a disease of the peripheral nervous system, CNS involvement is reported in the literature in several CMT patients by variations in the MFN2, PMP22, GJB1, GDAP, MORC-2, NDRG1 and NEFL genes." (PMID 37238449, 2023).
NDRG1 also shares sentences with these, for which no sentence is quoted: invasive breast carcinoma (5 papers); thyroid cancer (3); acute myeloid leukemia (2); Clear Cell Renal Cell Carcinoma (2); Ewing sarcoma (2); oral squamous cell carcinoma (2); acute lymphoblastic leukemia (1); adenocarcinoma (1); autoimmune disease (1); B-cell lymphoma (1); benign mole (1); bone metastasis (1); cervical squamous cell carcinoma (1); Charcot Marie Tooth neuropathy (1); Charcot-Marie-Tooth disease type 4 (1); chronic hepatitis B (1); CNS-tumors (1); cutaneous squamous cell carcinoma (1); depression (1); endometrial adenocarcinoma (1); epidermoid carcinoma (1); experimental autoimmune encephalomyelitis (1); ganglioneuroma (1); gastric ulcer (1); gastrointestinal tumors (1); hemangioblastoma (1); hemangioma (1); hematological malignancies (1); hereditary motor and sensory neuropathy (1); Hypercalcemia (1).
A further 31 diseases each share a sentence with NDRG1 in 1 paper.